ADAMTS13 (ADAM metallopeptidase with thrombospondin type 1 motif 13)
Diseases named in the same sentence as ADAMTS13 in open-access papers (continued):
Sharing a sentence is not in itself a finding about the gene and the disease.
thrombotic microangiopathy (continued). "Any symptom of TTP that reappears after remission—a decline in ADAMTS13 activity or clinical or biochemical indicators of thrombotic microangiopathy—is referred to as a relapse." (PMID 40757115, 2025). "This expert panel recommendation emphasizes the importance of standardized ADAMTS13 testing to support better diagnosis and timely treatment, especially in patients with thrombotic microangiopathies." (PMID 40725629, 2025). "Additional studies have expanded the clinical application of ADAMTS13 testing beyond thrombotic microangiopathies into liver diseases, as reduced ADAMTS13 levels directly correlate with the progression and severity of liver cirrhosis." (PMID 40725629, 2025). "Although extreme deficiency of ADAMTS13 is highly specific for a diagnosis of TTP, lesser reductions are observed in other thrombotic microangiopathies including haemolytic uraemic syndrome, sepsis and malignancy." (PMID 39274365, 2024). "Recombinant human ADAMTS13 (rhADAMTS13) has been evaluated in animal models of thrombotic microangiopathy." (PMID 39274365, 2024). "TTPa is a rare nosological entity hallmarked by TMA and dysfunctional ADAMTS13 enzymatic activity, with a challenging diagnosis considering its acute nature with signs and symptoms common to other thrombotic microangiopathies and high mortality." (PMID 39618627, 2024). "Congenital thrombotic thrombocytopenic purpura (cTTP) is a thrombotic microangiopathy (TMA) characterized by severe hereditary ADAMTS13 (a disintegrin and metalloproteinase with thrombospondin type 1 motifs 13) deficiency caused by ADAMTS13 mutations." (PMID 39845832, 2024). "Elevated levels of vWf and PAI-1, and decreased ADAMTS-13 activity, demonstrate that COVID-19 is an endotheliopathy that shares features with thrombotic microangiopathy." (PMID 37175942, 2023). "Recently, it has been documented that thrombotic microangiopathy can occur, especially in the most severe forms, in the context of SARS-CoV-2 infection and that reduced levels of ADAMTS13 are associated with a poor prognosis." (PMID 35189860, 2022). "Due to the amelioration of the thrombotic microangiopathy parameters along the PLEX sequence, this reduction in platelet count cannot be explained through a relative ADAMTS13 deficiency." (PMID 35314740, 2022). "An important role, in the context of thrombotic microangiopathies, is played by the ADAMTS13 (a disintegrin and metalloproteinase with a thrombospondin type 1 motif, member 13) plasma protease." (PMID 35189860, 2022). "Evidence of reduced ADAMTS13 activity in the presence of schistocytes (~ 2–4%) appeared compatible with thrombotic microangiopathy (TMA) secondary to COVID-19." (PMID 33058027, 2021). "Suppressed ADAMTS13 activity less than 10% is a cause of TTP, showing remarkable platelet consumption leading to thrombotic microangiopathy (TMA)." (PMID 33712048, 2021). "Since the activation of ADAMTS13 was reduced remarkably, the thrombotic tendency was determined to be a thrombotic microangiopathy-like condition owing to increased vWF." (PMID 34090366, 2021). "The presence of (at least localized) thrombotic microangiopathy is supported by observations of abnormal von Willebrand factor/ADAMTS-13 ratios." (PMID 33368021, 2021). "Mounting VWF/ADAMTS13 imbalance, culminating in the accumulation of uncleaved VWF molecules has been shown to increases the risk of developing secondary thrombotic microangiopathy in sepsis." (PMID 33058027, 2021). "For patients with thrombotic microangiopathy, thrombospondin type 1 motif, member 13 (ADAMTS13), antiphospholipid, and complement panel will be performed." (PMID 33195337, 2020). "Both changes are characteristic for the presence of thrombotic microangiopathy (TMA) with ongoing hemolysis as a consequence of low ADAMTS13 activity." (PMID 32122366, 2020). "vWFpp/ADAMTS13 ratio should be further studied as a useful marker for diagnosis of thrombotic microangiopathy postliver transplantation." (PMID 31998483, 2019).
thrombotic microangiopathy (continued). "In thrombotic microangiopathies (TMA) (i.e., TTP and HUS), ADAMTS13 deficiency has been associated with abnormal complement activation." (PMID 28634421, 2017). "ADAMTS13 is the main VWF-cleaving protease and its deficiency results in development of thrombotic microangiopathy." (PMID 28139439, 2017). "Human immunodeficiency virus (HIV) is a rare cause of thrombotic microangiopathies (TMA), that can present either with normal ADAMTS13 activity (referred as HIV-related TMA) or suppressed ADAMTS13 activity (referred as HIV-related acquired thrombotic thrombocytopenic purpura, aTTP)." (PMID 41555103, 2026). "The observations of this study demonstrate a wider interest in ADAMTS13 as a prognostic marker in different clinical settings outside of thrombotic microangiopathies and, therefore, follow a scientific trend of new clinical ADAMTS13 characterization and alternative use." (PMID 40725629, 2025). "In addition to TTP, ADAMTS13 measurement is essential in diagnosing other thrombotic microangiopathies, such as hemolytic uremic syndrome (HUS)." (PMID 40725629, 2025). "Although ADAMTS13 testing has become a key diagnostic tool in thrombotic microangiopathies, its broader clinical relevance is not yet well defined." (PMID 40725629, 2025). "We assessed the clinical utility of the assay in pediatric patients who (i) developed transplant‐associated thrombotic microangiopathy (TA‐TMA), (ii) have low ADAMTS13 activity, and (iii) develop acquired von Willebrand disease due to extracorporeal membrane oxygenation (ECMO) support." (PMID 41047907, 2025). "ADAMTS13, a metalloprotease responsible for cleaving ultra-large von Willebrand factor (vWF) multimers, plays a crucial role in regulating platelet aggregation and preventing thrombotic microangiopathy." (PMID 40868959, 2025). "Typical TTP is broadly defined as a thrombotic microangiopathy occurring in the context of severe ADAMTS13 deficiency (<10%), while ADAMTS13 is usually not decreased in HUS." (PMID 41160661, 2025). "Lastly, the release of IL-6 may at least in part account for the high levels of circulating VWF, but also in the decrease of ADAMTS13 activity, leading to a pro-aggregant phenotype and thrombotic microangiopathy-like features." (PMID 38915768, 2024). "Different scores use clinical data to predict the risk of thrombotic microangiopathy with and without severe ADAMTS13 deficiency." (PMID 39185293, 2024). "ADAMTS13 activity is typically normal or only slightly reduced (by more than 20%) in other forms of thrombotic microangiopathy that are secondary to hematopoietic progenitor cell transplantation, infection, disseminated malignancy, or hemolytic uremic syndrome." (PMID 38203218, 2023). "It has been hypothesised that the imbalance of VWF and ADAMTS-13 in COVID-19 may promote multi-organ thrombosis with a clinical picture of thrombotic microangiopathy." (PMID 35189860, 2022). "Additionally, abnormal levels of ADAMTS13 were found to participate in the progress of the thrombotic microangiopathies, stroke and cardiovascular diseases." (PMID 35011462, 2021). "We speculate that in acquired TTP, wherein significant levels of autoantibodies to ADAMTS13 are present, dosing of the M5 variant mRNA may provide sustained levels of enzyme activity to decrease ULMW-vWF and prevent thrombotic microangiopathies." (PMID 29777164, 2018). "Dysfunctional activation of the VWF/ADAMTS13 system in thrombotic microangiopathies (TMAs) (such as TTP, HUS, and DIC) results in microvessel occlusion by a complex web of VWF-rich thrombi causing tissue hypoperfusion and organ failure, potentially life-threatening." (PMID 28634421, 2017). "However, only in the presence of severe ADAMTS-13 deficiency (level<6%), ultra-large VWF multimers accumulate, causing thrombotic microangiopathies." (PMID 23383177, 2013).
thrombotic microangiopathy (continued). "This functional interaction between fH, VWF and ADAMTS-13 could contribute to the pathogenesis of thrombotic microangiopathy in both TTP and aHUS and provide a mechanistic basis for the frequently observed clinical overlap between TTP and HUS." (PMID 23991205, 2013). "However, diagnosis remains challenging when borderline ADAMTS13 activity levels fluctuate between 10–20%, as alternative thrombotic microangiopathies could be differentially diagnosed." (PMID 37834813, 2023). "SARS-CoV-2 thereby increases the risk of thrombotic microangiopathy by potentially two synergistic mechanisms: First, the ubiquitous endothelial damage induces an excessive release of VWF, exceeding the protease activity of physiological concentrations of ADAMTS13." (PMID 37380654, 2023). "Furthermore, contents released from activated neutrophils or NETs induce the reduction of ADAMTS13 activity, which may occur in both thrombotic microangiopathies (TMAs) and acute ischemic stroke (AIS)." (PMID 33343584, 2020). "Notably, the patient had one similar episode of hypertension-induced thrombotic microangiopathy within a period of the last three months and ADAMTS-13 (a disintegrin and metalloprotease with thrombospondin type 1 motif 13) activity was normal on his previous admission." (PMID 30410841, 2018). "The presence of reduced ADAMTS13 activity may contribute to the pathophysiological changes observed in severe malaria and particularly to microvascular disorders as observed in other groups of thrombotic microangiopathy." (PMID 24812562, 2014). "Recently, infusion of shiga toxin has been shown to support the development of a thrombotic microangiopathy in ADAMTS13-deficient mice, but the effect of the infusing botrocetin on ADAMTS13 or in the absence of ADAMTS13, if any, is unknown." (PMID 22091368, 2010). "The literature contains several reports of concurrent thrombotic microangiopathy and DKA in both pediatric and adult patients; however, ADAMTS-13 activity below 10% was observed in only one previous case." (PMID 40390002, 2025). "TTP is a relatively rare, life-threatening condition that comprises thrombotic microangiopathy (TMA) and enzymatic dysfunction of ADAMTS13 (a disintegrin-like metalloproteinase with thrombospondin motif type 1, member 13, which regulates platelet aggregation)." (PMID 40486424, 2025). "Because the signs, symptoms, and laboratory markers overlap with other thrombotic microangiopathies, the distinction of a TTP diagnosis relies on determination of ADAMTS13 activity." (PMID 35479064, 2022). "In the same line, in primates, the injection of human anti-ADAMTS-13 neutralizing autoantibody provokes a transient biological thrombotic microangiopathy but not a severe disease responsible for organ failure." (PMID 36944989, 2023). "In one cross-sectional study of 772 patients with a first episode of thrombotic microangiopathy and ADAMTS13-confirmed diagnosis of TTP, 73% of patients were noted to have positive anti-ADAMTS13 IgG, with an additional 3% being identified beyond the first episode." (PMID 37568288, 2023). "It is assumed that the imbalance between vWF and ADAMTS-13 in COVID-19, including a decrease in the level and activity of ADAMTS-13, may create microthrombotic conditions leading to secondary thrombotic microangiopathy." (PMID 35887770, 2022). "The measurement of ADAMTS13 antigen levels and enzyme activity is important for TTP diagnosis, and to distinguish the clinical symptoms of this disease from other thrombotic microangiopathies like Hemolytic-Uremic Syndrome (HUS), disseminated intravascular coagulation (DIC) and the HELLP syndrome." (PMID 25992814, 2015). "In this clinical setting, ADAMTS-13 is present at a normal level, sufficient to proteolyze in part UL-VWF multimers, at variance with the situation observed in canonical forms of thrombotic microangiopathies, where ADAMTS-13 is <6%." (PMID 23383177, 2013).
thrombotic microangiopathy (continued). "Therefore, the measurement of ADAMTS13 also serves as an exclusion biomarker to rule out TTP in pregnancy-related thrombotic microangiopathies." (PMID 40725629, 2025). "Therefore, it is not surprising that vWF /ADAMTS13 axis can be involved in the thrombotic microangiopathy observed during COVID-19 outside pregnancy." (PMID 35189860, 2022). "We eventually diagnosed thrombotic microangiopathy because her ADAMTS13 activity was not reduced." (PMID 30089509, 2018). "However, once the ADAMTS13 test returned negative, plasma exchange was stopped and the patient's profile returned to normal with supportive care and aggressive blood pressure control, as she had hypertension-induced thrombotic microangiopathy." (PMID 37007424, 2023). "Additionally, since ADAMTS13 activity was not used as an inclusion criterion, patients with other types of thrombotic microangiopathy may have been included among our cohort." (PMID 37568558, 2023). "Moreover, oxidative stress may also induce accumulation of high molecular weight VWF multimers (UL-VWF), although at a minor extent than in thrombotic microangiopathies, where ADAMTS-13 is strongly reduced or absent so that proteolytic processing of UL-VWF multimers is severely defective." (PMID 23383177, 2013). "Although the ADAMTS13 test was not performed for technical reasons, considering hemolysis parameters, haptoglobin, LDH, and bilirubin were within the reference range, and the suspicion of thrombotic microangiopathy (TMA) was excluded." (PMID 39860022, 2025). "However, we attempted to mitigate this by only including cases with the FAERS code “TTP”, whereas 104 distinct cases of “Thrombotic Microangiopathy” without a diagnosis of TTP (and theoretically therefore without a significant reduction in ADAMTS13 activity) were not included." (PMID 39883995, 2025).
COVID-19 (98 papers, 2020 to 2026). A disease caused by infection with severe acute respiratory syndrome coronavirus 2. "Evidence from thromboinflammatory conditions, including COVID-19, indicates that elevated vWF levels combined with reduced ADAMTS13 activity are associated with disease severity and thrombotic risk." (PMID 41007843, 2025). "Regarding the association between COVID-19 and coagulation abnormalities, data from the literature suggest that while the von Willebrand factor (vWF) is upregulated, ADAMTS13, a metalloprotease that cleaves high-molecular-weight vWF, is downregulated." (PMID 40564774, 2025). "Our chromatin conformation analyses provide evidence that non-coding variants in ABO, associated with VWF levels, VTE risk, and COVID-19 severity, are in spatial proximity to ADAMTS13 in endothelial cells." (PMID 41311061, 2025). "Disruption of the vWF-ADAMTS13 axis, characterized by elevated vWF and reduced ADAMTS13 activity has been implicated in thrombotic disorders, including COVID-19-asscoiated coagulopathy, where this imbalance correlates with disease severity and mortality." (PMID 41007843, 2025). "While mild to moderate reductions in ADAMTS-13 activity have been observed, possibly associated with markedly increased VWF levels, severe ADAMTS-13 deficiency appears to be rare in COVID-19." (PMID 40993743, 2025). "The nasopharyngeal swab confirmed the diagnosis of COVID-19 by RT-PCR, and plasma ADAMTS-13 activity was completely deficient (0%)." (PMID 39969357, 2024). "We conclude that low ADAMTS13 activity in obese individuals is correlated with a high risk of COVID-19 severity and slower viral clearance than in those with normal BMI, but without a significant correlation between patient BMI and ADAMTS13 activity." (PMID 38608066, 2024). "As well as an association with severity of infection, ADAMTS13 activity has been shown in several studies to be associated with mortality in COVID-19." (PMID 39274365, 2024). "In our study, it negatively correlated with ADAMTS13, and low ADAMTS13 levels have been shown to be associated with a more severe COVID-19 phenotype." (PMID 39237986, 2024). "Deficiency of plasma ADAMTS-13 activity was observed in critical and severe COVID-19 patients compared to healthy controls." (PMID 37175942, 2023). "In summary, the present findings show that the higher VWF concentrations and the lower ADAMTS13, the higher the probability of a severe course of COVID-19 including risk of death." (PMID 37380654, 2023). "The present study demonstrates for the first time, that generation of ADAMTS13 antibodies is frequent in COVID-19, associated with lower ADAMTS13 activity and increased risk of an adverse disease course." (PMID 37380654, 2023). "The primary mechanisms of TMA in COVID-19 patients are complement-mediated disease and acquired deficiency of ADAMTS13." (PMID 37046448, 2023). "In particular, a prospective cohort observational study identified several abnormal variants of complement factor H, C5b-9 (ADAMTS-13) in patients with COVID-19 who developed atypical hemolytic syndrome." (PMID 37626703, 2023). "Decreased serum ADAMTS13 levels correlate with increased hospitalization risk in COVID-19 patients and poor outcomes." (PMID 36941580, 2023). "For example, we identified rs149181677, the variant located on the ADAMTS13 gene, was shared between COVID-19 and VTE." (PMID 37085521, 2023). "The present retrospective analysis shows, that PLEX is able to reduce the excess of vWf, to increase ADAMTS13 activity, to readjust the ADAMTS13/vWf:Ag ratio and thereby to reduce the risk of immunothrombosis in COVID-19." (PMID 35314740, 2022). "A number of studies have reported an imbalance of VWF and ADAMTS-13 in COVID-19 patients, which is associated with a high thrombotic risk." (PMID 35215805, 2022). "The disbalance between ADAMTS13 and vWf represents a further crucial pathomechanism of COVID-19 associated immunothrombosis." (PMID 35314740, 2022).